NEDD4L (NEDD4 like E3 ubiquitin protein ligase)
Diseases named in the same sentence as NEDD4L in open-access papers (continued):
Sharing a sentence is not in itself a finding about the gene and the disease.
tumor (92 papers, 2013 to 2026). "Despite the high NEDD4L mutation frequency in BRAFi-treated tumors in our screen, NEDD4L overexpression alone provided a modest increase in tumor growth in the presence of BRAFi treatment in vivo." (PMID 38213996, 2024). "In contrast to prior research perspectives that NEDD4L acts as a tumor suppressor, recent studies have implicated it also acts as an oncogene in certain contexts." (PMID 39557844, 2024). "Here, the results from our clinical data showed that NEDD4L expression is low and associated with tumor invasion, lymph node metastasis and distant metastasis." (PMID 39557844, 2024). "NEDD4L can also inhibit the expression of various tumor-associated membrane proteins, including LGR5, beta-catenin, and transforming growth-factor beta (TGFβ) receptor." (PMID 37240137, 2023). "Low NEDD4L expression is associated with larger tumor size, increased vascular invasion, lower differentiation, more lymph node and distant metastases, and progressive tumor stage." (PMID 38027016, 2023). "By analyzing the mutation databases in TCGA and COSMIC, we found that the main mutations of tumor-related NEDD4L are G39V, P197S, S230F, and R253W." (PMID 37240137, 2023). "Tumor-associated substrates of NEDD4L have been identified in numerous pathway proteins and membrane receptors." (PMID 38027016, 2023). "More importantly, suppression of glutamine metabolism caused by NEDD4L overexpression also inhibited tumor growthin vivo." (PMID 35593463, 2022). "The data imply that upregulation of Rspo‐Lgr5 signalling upon Nedd4/Nedd4l loss increases tumour predisposition and progression in Apcmin animals by promoting Wnt activation and ISC self‐renewal." (PMID 31867777, 2020). "NEDD4L affects tumor-associated pathways through ubiquitination and plays an important role in tumorigenesis and development." (PMID 31673244, 2019). "Moreover, we find that loss of endothelial NEDD4L significantly enhances tumor growth and promotes angiogenesis in vivo." (PMID 40567051, 2025). "Next, we asked if the tumour‐promoting role of Nedd4 and Nedd4l was associated with Wnt signalling." (PMID 31867777, 2020). "Of note, loss of Nedd4l appears to be more effective in tumour progression than Nedd4 ablation." (PMID 31867777, 2020). "This NEDD4L ubiquitination is affected by hypoxic stress in tumor tissues; therefore, we hypothesized that NEDD4L might be associated with hypoxia-inducible gene HIF-1α." (PMID 31673244, 2019). "Overall, NEDD4L plays a crucial role in inhibiting tumor angiogenesis by regulating eEF1A1 ubiquitination and degradation, providing new insights into the NEDD4L-eEF1A1 axis and its potential as a therapeutic target." (PMID 40567051, 2025). "In this study, we investigate the mechanisms by which NEDD4L influences the function of human umbilical vein endothelial cells (HUVECs) and its effect on tumor angiogenesis." (PMID 40567051, 2025). "For instance, NEDD4 has been shown to function as a tumor promoter in colorectal cancer, highlighting the complexity of its role in tumorigenesis; whereas, NEDD4L functions as a tumor suppressor by controlling Wnt signaling pathway." (PMID 41385185, 2025). "Our study demonstrated that NEDD4L acts as a tumor suppressor in GC, while BICC1 functions as a pro‐tumorigenic factor." (PMID 39717922, 2025). "It was found that the tumor tissues from GC patients had significantly reduced levels of NEDD4L mRNA and protein." (PMID 39717922, 2025). "The present study's findings consistent with the NEDD4L findings reported in the literature, indicating that NEDD4L functions as a tumor suppressor gene." (PMID 39717922, 2025). "Thirty GC patients were enrolled in this study to assess the expression of BICC1 and NEDD4L in tumor samples." (PMID 39717922, 2025). "Conversely, our previous work revealed that the tumor-suppressive circNEIL3 inhibits tumor metastasis by recruiting the E3 ubiquitin ligase Nedd4L to facilitate degradation of the oncogenic protein YBX1." (PMID 41049614, 2025).
tumor (continued). "As revealed by the esophageal carcinoma tumor bearing model, high NEDD4L expression markedly suppressed tumor growth." (PMID 38831335, 2024). "We further performed IHC scoring on 142 cases of ESCC, and uncovered that NEDD4L expression negatively connected with tumor invasion (p < 0.05), lymph node metastasis (p < 0.05) and distant metastasis (p = 0.001)." (PMID 39557844, 2024). "It is important to note that while three of the four subclones harboring both BRAF and NEDD4L insertions were detected within the same tumor mass, each subclone is defined by completely independent transposon insertion events." (PMID 38213996, 2024). "NEDD4L plays a critical role in regulating cancer stem cells and the functions of tumour cells, proliferation, apoptosis, cell cycle regulation, migration, invasion and epithelial–mesenchymal transition, as well as tumour drug resistance." (PMID 39317954, 2024). "An important role of Nedd4L is that of a tumor suppressor; it is most often downregulated in cancer cells." (PMID 39015146, 2024). "Meanwhile, tumour weight was elevated after NEDD4L silencing and significantly reduced after KLF5 inhibition." (PMID 39317954, 2024). "We further investigated the proliferation, invasion and migration of ESCC cells and observed tumour growth in vivo after modulating NEDD4L and KLF5." (PMID 39317954, 2024). "In our study, integrated bioinformatics analysis indicated that low expression of NEDD4L and high expression of RAC2 were both associated with poor prognosis of ccRCC, pro-tumorigenic immunity, and multiple tumor-associated pathways." (PMID 39596003, 2024). "According to our results, potential strategies to overcome the challenges posed by spatial heterogeneity, such as combination therapies or localized delivery methods, to enhance the targeting of the NEDD4L/KLF5 axis across different tumour regions." (PMID 39317954, 2024). "NEDD4L expression was declined in ESCC and was associated with tumor invasion, lymph node metastasis and distant metastasis." (PMID 39557844, 2024). "NEDD4L expression was significantly inhibited in IECs of adjacent tumor and tumor tissues from CAC mice compared with the distal normal colon." (PMID 39688910, 2024). "NEDD4L inactivation desensitized ESCC cells to ferroptosis through upregulating xCT function and loss of NEDD4L stimulated tumor growth in xenograft mouse models." (PMID 39557844, 2024). "NEDD4L expression was low and served as a good prognosis marker in clinical samples, as well as negatively regulated xCT expression and blocked tumor growth in ESCC." (PMID 39557844, 2024). "The results indicated that silencing NEDD4L increased tumor growth speed compared to the control group in vivo." (PMID 39557844, 2024). "Our initial genetic analysis of bulk tumor samples identified several novel candidate genes, including NEDD4L and VGLL3." (PMID 38213996, 2024). "The Nedd4 enzyme is a known oncogene, whereas Nedd4L has the opposing function as a tumor suppressor." (PMID 39015146, 2024). "This suggested that the inhibition of NEDD4L expression was a consequence of dysregulated intestinal homeostasis, including inflammation damage and tumor formation." (PMID 39688910, 2024). "PD-L1 is shown to be a substrate for NEDD4L, which inhibits PD-L1 levels via ubiquitination to enhance the anti-tumor immune response of NSCLC." (PMID 38027016, 2023). "Current research works clearly suggest that NEDD4L has tumor-suppressive effects because of its ability to modulate oncogenic proteins." (PMID 37568787, 2023). "Recently, it was reported that NEDD4L is aberrantly expressed in tumors and regulates tumorigenesis and tumor development." (PMID 38027016, 2023). "In MM cancer cells, NEDD4L favors a tumor suppressive role and positively regulates autophagy initiation via the inhibition of mTORC1 as well as the phagophore elongation via increasing lipidation of LC3-I to LC3-II." (PMID 36918822, 2023).
tumor (continued). "Several studies have reported the low expression of NEDD4L in tumor tissues, including mRNA and protein expression, indicated its role as a tumor suppressor in specific types of cancer." (PMID 38027016, 2023). "Of note, the most important and extensive role NEDD4L plays in regulating tumor cell function is in ubiquitinating substrates." (PMID 38027016, 2023). "In summary, the present study has demonstrated that KSRP acts as a tumor promoter in ccRCC, and NEDD4L is a critical determinant and is negatively regulated by KSRP to execute its prometastatic effect via EMT induction." (PMID 37580757, 2023). "NEDD4L also acts as a tumor suppressor and negatively regulates autophagy initiation via destabilizing ULK1 and ASCT2." (PMID 36918822, 2023). "NEDD4L primarily functions as a tumor suppressor in several tumors but also plays an oncogenic role in certain tumors." (PMID 38027016, 2023). "As a key tumor suppressor in human cancer, NEDD4L regulates the ubiquitin-mediated degradation of oncoproteins." (PMID 37759298, 2023). "Several studies have reported that NEDD4L promoted apoptosis in tumor cells by downregulating downstream pathways." (PMID 38027016, 2023). "Consistent with our in vitro results, expression levels of WT1 were positively correlated with KSRP and negatively correlated with NEDD4L levels in tumor specimens from two independent ccRCC cohorts." (PMID 37580757, 2023). "NEDD4L is an E3 ubiquitin ligase and was reported to function as a tumor suppressor in most cancer types via elevating the degradation of diverse substrates." (PMID 37580757, 2023). "NEDD4L, an E3 ubiquitin ligase, has recently been identified as a tumour suppressor in many types of human cancers." (PMID 35646490, 2022). "Overexpression of NEDD4L significantly suppressed cell proliferation, migration and invasion abilities, whereas knockdown of NEDD4L enhanced the tumor metastasis of NSCLC cells." (PMID 35270630, 2022). "In vivo study showed that overexpressing NEDD4L also significantly inhibited tumor growth, suppressed tumor cell proliferation, and inhibited the expressions of GLS1 and SLC1A5 in tumor tissue." (PMID 35593463, 2022). "The results from qRT-PCR analysis showed that the expression of Notch2, NICD, Hes1, and Hey1 in murine tumor tissues from NEDD4L-overexpressed group was significantly decreased compared with control group." (PMID 35646490, 2022). "Another in vitro study showed that NEDD4L can act as a tumor suppressor, and it is downregulated in NSCLCs." (PMID 36293239, 2022). "In the following study, the reason for NEDD4L repression (genetic alterations or epigenetic modification) in tumour tissues will been further investigated." (PMID 35646490, 2022). "In conclusion, our investigation clarified that NEDD4L exerts tumor-suppressive activity in MM, similar to its homolog NEDD4-1." (PMID 35236820, 2022). "The results showed that NEDD4L overexpression significantly inhibited tumor growth in vivo, while knockdown of NEDD4L remarkably promoted tumor proliferation." (PMID 35090513, 2022). "Especially, overexpression of NEDD4L in LUAD cells markedly inhibited tumour growth of LUAD xenografts in nude mice, indicating that NEDD4L functions as a tumour suppressor in LUAD." (PMID 35646490, 2022). "Because the mTOR signaling pathway is closely related to tumor proliferation, we explored the effect of NEDD4L on its activity in LUAD cells." (PMID 35090513, 2022). "Mechanistic study indicates that NEDD4L regulates tumor progression through ubiquitination of c-Myc and modulation of glutamine metabolism." (PMID 35593463, 2022). "Overexpression of NEDD4L in A549 cells markedly repressed tumour growth of LUAD xenografts in nude mice." (PMID 35646490, 2022). "Neural precursor cell expressed developmentally down-regulated 4-like protein (NEDD4L), an E3 ubiquitin ligase, exerts an important role in diverse biological processes including development, tumorigenesis, and tumor progression." (PMID 35646490, 2022).
tumor (continued). "It has been reported that NEDD4L exerts a tumor-suppressive role by promoting PI3K ubiquitination and downregulation." (PMID 35236820, 2022). "ACSL3, EPAS1, FASN, GSTP1, LDHB, and NEDD4L were identified as the candidate genes through the intersection of tumor-related genes, DEGs, and ferroptosis-related genes." (PMID 35223835, 2022). "Here we showed that NEDD4L acted as a tumor suppressor in LUAD with following lines of supporting evidence." (PMID 34838005, 2021). "In TCGA_KIRC and GSE40435 data sets, the correlation between the expression of NEDD4L and other genes in tumor samples was analyzed." (PMID 34458018, 2021). "NEDD4L, on the other hand, is a tumor suppressor that targets various oncogenic proteins for degradation." (PMID 34838005, 2021). "NEDD4L has been widely reported to modulate multiple signaling pathways in tumor cells through the ubiquitination and degradation pathways." (PMID 37305161, 2021). "After that, to further investigate the role of ubiquitination of SphK2 in vivo, a xenograft tumor-bearing model was established by inoculating NEDD4L overexpression plasmid and/or SphK2 overexpression plasmid transfected U251 into nude mice." (PMID 34305532, 2021). "Select a tumor type whose NEDD4L gene expression significantly affects the prognosis of patients, and focus on how NEDD4L affects the malignant phenotype of tumor cells." (PMID 34539897, 2021). "Consistent with this, nedd4L has been reported as a tumor suppressor by regulating several protein targets, such as LGR5 and DVL2." (PMID 34769140, 2021). "NEDD4L has been reported to promote the degradation of certain proteins involved in tumor signaling pathways, including Dvl2 and Smad2/Smad3." (PMID 34838005, 2021). "Consistently, NEDD4L knockdown also partially reversed the effect of FTO deletion on tumor growth in vivo." (PMID 33846348, 2021). "A great amount of evidence has demonstrated that NEDD4L mainly functions as a tumor suppressor in most cancer types, while it also acts as an oncogene in a few cancers." (PMID 34869021, 2021). "This review focuses on the potential role and related molecular mechanisms of NEDD4L in carcinogenesis and tumor progression." (PMID 34869021, 2021). "Consistent with previous reports, this study suggested that NEDD4L acts as a tumor suppressor in ccRCC." (PMID 34458018, 2021). "It was found that NEDD4L overexpression resulted in reduced tumor growth speed and weight, while the presence of M2-EVs exerted a tumor-promoting effect." (PMID 37305161, 2021). "Herein, we reported that NEDD4L had tumor suppressor activity to be against LUAD cells and blocked oncogenic function of UBE2T." (PMID 34838005, 2021). "Propidium iodide (PI) staining, revealed that the number of dead cells is increased using specific shRNA to knock out NEDD4L, and the colony formation assay confirmed that NEDD4L knockout enhances tumour suppression induced by erastin and RSL3." (PMID 34503532, 2021). "Tumor immune microenvironment analysis found that NEDD4L gene expression is negatively correlated with stromal cell infiltration level and immune cell infiltration level in most cancer types." (PMID 34539897, 2021). "In most cancer types (20 in 34 types, p-value <0.05), the expression of NEDD4L is negatively correlated with the infiltration value of interstitial cells and immune cells in tumor tissues." (PMID 34539897, 2021). "The results of protein interaction analysis in Pathway Common also showed that MAPK upstream kinases (MAP3K3, MAP3K5), ERBB3 and ULK1, which are important for tumor cell growth and proliferation, can bind to NEDD4L." (PMID 34539897, 2021). "Among all these genes, we elected to initially focus on NEDD4L, as it is found to be downregulated in several cancers, suggesting a tumor-suppressive role for NEDD4L." (PMID 33846348, 2021).
tumor (continued). "NEDD4L, which was downregulated in samples with high tumor-infiltrating lymphocytes scores, has been shown to be a negative regulator of Wnt-signaling —a pathway often perturbed in cancer." (PMID 32605588, 2020). "According to the datasets from TCGA and the GSE9348, the transcript levels of NEDD4L in tumor tissues from CRC patients were significantly (P < 0.001) lower than those in normal tissues." (PMID 33117809, 2020). "In conclusion, our work shows that NEDD4 and NEDD4L are crypt‐expressing tumour suppressors by targeting the RSPO receptor LGR5 and DVL2 for degradation." (PMID 31867777, 2020). "Overall, the results suggest that NEDD4L plays a key role in suppressing tumor progression by inhibiting autophagy and mitochondrial respiratory function." (PMID 31959741, 2020). "Inactivation of NEDD4 and NEDD4L increases Wnt activation and ISC numbers, which subsequently enhances tumour predisposition and progression." (PMID 31867777, 2020). "Herein, we investigated the mechanisms by which ULK1 is modulated by an E3 ubiquitin ligase, NEDD4L, and suggest the physiological significance of these molecular regulations on tumor progression." (PMID 31959741, 2020). "Here, we investigate the role of NEDD4 and NEDD4L in the context of intestinal homeostasis and tumour development." (PMID 31867777, 2020). "The Cancer Genome Atlas (TCGA) datasets (TCGA 2012 provisional; cbioportal.org) showed that NEDD4L levels were downregulated in multiple human tumor patients, and were inversely correlated with clinical outcome." (PMID 31959741, 2020). "Our data demonstrate that both Nedd4 and Nedd4l exacerbate Apcmin tumour phenotype, indicating that they are both tumour suppressors." (PMID 31867777, 2020). "An increasing number of researches indicated that NEDD4L was related to some tumor progression pathways and was found abnormally expressed in several kinds of solid cancers." (PMID 31775867, 2019). "Multivariate analysis revealed that for overall survival in GC patients, tumor differentiation and the combined expression of NEDD4L and HIF-1α were independent prognostic factors." (PMID 31673244, 2019). "The low expression of NEDD4L significantly correlated with tumor invasion (P = 0.025), tumor differentiation (P = 0.039) and TNM staging (P = 0.03)." (PMID 31673244, 2019). "TGF-β3 was upregulated 8.8-fold in DC-tumor fusions, but the observed downregulation of the TGFβ-induced protein in combination with upregulation of NEDD4L argues against a major impact of this cytokine on fusion cells." (PMID 26605345, 2015). "The significant decrease in NEDD4L expression in CRC suggests the possibility that NEDD4L plays a tumor-suppressive role in CRC." (PMID 24312311, 2013). "Taken together, these findings suggest that NEDD4L has the potential to act as a tumor suppressor in CRC." (PMID 24312311, 2013). "However, the exosomes secreted by M2 macrophages upregulate miR-3679-5p in the tumor cells and inhibit the secretion of the regulatory factor NEDD4L, which decreases the stability of c-Myc and desensitizes the tumor cells to cisplatin." (PMID 39757995, 2025). "In contrast, low expression of NEDD4L (OS: HR = 0.75, RFS: HR = 0.59, PPS: HR = 0.53) and SELENBP1 (OS: HR = 0.65, RFS: HR = 0.56, PPS: HR = 0.64) was associated with poor prognosis, suggesting a protective role by inhibiting tumor progression." (PMID 40959565, 2025). "Tumor tissues and GC cells exhibited low expression levels of NEDD4L." (PMID 39717922, 2025). "We infused NK-92 cells overexpressing NEDD4L and its three substrates into tumor-bearing Hu-SRC mice to evaluate whether NEDD4L-inhibited ferroptosis improved NK cell antitumor immunity." (PMID 40399270, 2025). "Recent preclinical studies have further demonstrated that eEF1A1 degradation via the NEDD4L-mediated ubiquitin–proteasome pathway suppresses tumor angiogenesis by inhibiting endothelial cell proliferation and migration, highlighting its therapeutic potential in antiangiogenic therapy." (PMID 40806463, 2025).